IL4 (interleukin 4)
Diseases named in the same sentence as IL4 in open-access papers (continued):
Sharing a sentence is not in itself a finding about the gene and the disease.
nasal polyps (continued). "Increased levels of IL-4 have been found in the sinus mucosa and nasal polyps of AERD subjects." (PMID 22262978, 2012). "We previously found that IL‐4 and IL‐13 could induce periostin expression in nasal polyps." (PMID 34504680, 2021). "Furthermore, IL-4 has been known to increase transforming growth factor (TGF)-β in nasal polyps and therefore could be responsible for stromal cell proliferation." (PMID 34208325, 2021). "This study assessed dupilumab, a monoclonal antibody targeting IL-4 and IL-13 signaling, to evaluate its efficacy in reducing the disease burden in patients with CRS with nasal polyps (CRSwNP)." (PMID 39768876, 2024). "Wang et.al identified PD-1hiCXCR5−CD4+ T cells in nasal polyps that can be characterized by expression of IFN-γ, IL-17A, and IL-4, and PD-1hiCXCR5−CD4+ T cells can induce IgE production via IL-4 only in eosinophilic NPs." (PMID 37176151, 2023). "Th2 cytokines, such as IL-4 and IL-13, upregulate CCL17 expression in nasal polyp epithelium, whereas Th1 cytokines increase CCL17 levels in both normal and nasal polyp epithelium." (PMID 37762530, 2023). "The stimulation of cultured epithelial cells with Th2 cytokines, IL-4 and IL-5, resulted in higher CCL17 expression in nasal polyp epithelial cells when compared to normal ethmoid tissue." (PMID 35455762, 2022). "IL-4 is also involved in stimulating CC chemokine TRAC release from fibroblasts of nasal mucosa and nasal polyps that, in turn, facilitate Th2 cell migration." (PMID 36285981, 2022). "Levels of IL-4, IL-5, IL-13, and ECP and the eotaxins CCL11, CCL24, and CCL26 were elevated in the nasal polyps of patients with eCRSwNP or noeCRSwNP." (PMID 35747690, 2022). "In TGF-β1-stimulated nasal-polyp-derived fibroblasts, ECM genes and αSMA gene and protein were overexpressed, as well as αSMA in IL-4-stimulated fibroblasts." (PMID 35682987, 2022). "Type 2 inflammatory cytokines such as IL-4, IL-13, IL-8, and IL-33 in CRSwNP patients enhanced expression of MUC5AC in nasal polyp-derived epithelial cells." (PMID 36506304, 2022). "The CRSwNP mainly showed Th2 cell inflammation, mainly involving the effects of IL-4, IL-5, and IL-13, accompanied by changes in IL-25, IL-33, TSLP and IgE levels, with eosinophil infiltration and nasal polyps phenomenon." (PMID 36506304, 2022). "Primary human cultures of nasal-polyp-derived fibroblasts were established and stimulated by TGF-β1 and/or IL-4 and/or OSM." (PMID 35682987, 2022). "When the ethmoid and nasal polyp tissues of patients with CRS are examined, local T cell infiltration, mediators such as IL-4 and IL-5, and Th2-type cytokine profile dominance were observed in the ethmoid mucosa and nasal polyps of the patients with CRS." (PMID 34212158, 2021). "Indeed, the effect of IL-4/IL-13 and IL-5 on nasal epithelial repair was already showed but to date, no study has precisely described the role of IL-6, IL-9 and IL-10 (new ILs described in nasal polyposis) on human nasal epithelial cells in an in vitro wound repair model." (PMID 32209102, 2020). "The cytokine profile of nasal polyps in N‐ERD patients shows the typical components of a Th2 disease, as well as eosinophilia and significant upregulation of IL-4 and IL-5." (PMID 29564208, 2018). "In nasal polyps, IL-5 correlated highly with other Th2 cytokines: eotaxin, MCP-1, MCP-4, TARC, IL-4 and IL-13." (PMID 26132710, 2015). "Chronic rhinosinusitis with nasal polyps (CRSwNP) is a type 2 inflammatory disease that is often refractory to surgery and requires treatment with biologics, including dupilumab (DUP), a monoclonal antibody targeting IL-4/13." (PMID 41409935, 2025). "Our aim was to use detected IL-1, IL-4, IL-6, IL-7, IL-8, IL-10, IL-12, Ki 67, HBD-2, HBD-3, and LL-37 to classify specific inflammatory endotypes in chronic rhinosinusitis with the tissue of nasal polyps (CRSwNP)." (PMID 38791197, 2024).
nasal polyps (continued). "Our data confirmed that OSM, TGF-β1 and IL-4 were overexpressed in nasal polyps when compared to noninflammatory nasal mucosa." (PMID 35682987, 2022). "The exact pathophysiology of nasal polyposis is not completely explained, but recent studies demonstrated that it involves cytokines such as IL-5, IL-4 and IL-13." (PMID 35630042, 2022). "In nasal polyps and in noninflammatory nasal mucosa, we quantified by RT-qPCR the expression of TGF-β1, OSM and IL-4, which are known to be implicated in fibrotic processes." (PMID 35682987, 2022). "We confirmed that OSM, as TGF-β1 and IL-4 are overexpressed in nasal polyps by comparison to noninflammatory nasal mucosa." (PMID 35682987, 2022). "Then, we stimulated nasal-polyp-derived fibroblasts with TGF-β1 in the presence or absence of IL-4 and/or OSM." (PMID 35682987, 2022). "TGF-β1 (p < 0.0001), OSM (p = 0.003) and IL-4 (p = 0.013) were overexpressed in nasal polyps compared to noninflammatory mucosa." (PMID 35682987, 2022). "The purpose of this paper was to evaluate the level of Cyclooxygenase-2 (COX-2), Periostin (POSTN) and Interleukin-4(IL-4) gene expression in patients with chronic rhinosinusitis with nasal polyps, without polyps and with a nasal septum deviation." (PMID 25573836, 2015). "The purpose of this paper was to evaluate the level of CYCLOOXYGENASE-2 (COX-2), PERIOSTIN (POSTN), INTERLEUKIN-4 (IL-4) gene expression in patients with chronic rhinosinusitis: with nasal polyps, without polyps and with nasal septum deviation." (PMID 25573836, 2015). "Therefore, our aim was to use detected IL-1, IL-4, IL-6, IL-7, IL-8, IL-10, IL-12, Ki 67, HBD-2, HBD-3, and LL-37 to classify specific inflammatory endotypes in chronic rhinosinusitis with the tissue of nasal polyps (CRSwNP)." (PMID 38791197, 2024). "IL-4 accumulation leads to a shift from ILC1s toward ILC2s, which can be reversed by IL-12, in patients with severe chronic obstructive pulmonary disease (COPD) or chronic rhinosinusitis with nasal polyps, suggesting the induction of IL-12 and IL-4 signatures in ILC1s and ILC2s, respectively." (PMID 32117199, 2019). "In contrast, we could not find papers in the literature showing altered IL-4 values in patients with nasal polyposis and cystic fibrosis." (PMID 20339685, 2010). "There were also significant increases in GATA3, IL4, IL5, and IL17 gene expression levels in nasal polyp tissue from the AERD group compared with the non-AERD group." (PMID 38360807, 2024). "TGF-β1, IL-4 and OSM as well as αSMA were overexpressed in nasal polyps when compared to noninflammatory nasal mucosa." (PMID 35682987, 2022).
glioma (81 papers, 2002 to 2025). A benign or malignant brain and spinal cord tumor that arises from glial cells (astrocytes, oligodendrocytes, ependymal cells). "Research into the use of IL-2 in glioma patients began as early as 1986, and a phase I trial investigating a glioma cell vaccine transfected with a gene encoding IL-4 showed promising clinical responses in patients with HGGs." (PMID 40113789, 2025). "Schwartzbaum and colleagues found an association with reduced soluble interleukin 4 receptor alpha (sIL4RA) (OR=0.92, 95% CI=0.76-1.12) and elevated IL4-sIL4RA (OR=1.37, 95% CI=1.16-1.61) with increased risk of glioma in the JSB." (PMID 37265788, 2023). "Schwartzbaum and colleagues found pre-diagnostic glioma to be associated with increased IL4 levels (OR=1.13, 95% CI=0.90-1.43) in the JSB." (PMID 37265788, 2023). "There is a large number of macrophages infiltration in the glioma microenvironment, which is associated with a variety of factors secreted by tumor cells, including IL-4, IL-6, IL-10, TGF-β, microRNAs, macrophage colony-stimulating factor (M-CSF), and CCL2." (PMID 36483052, 2022). "Our cellular response to IL-4 gene risk signature was found to be strongly correlated with previously confirmed clinical features of gliomas including WHO grade, molecular subtypes, 1p/19q codeletion status and IDH status." (PMID 35203944, 2022). "Different gliomas secrete IL-4, and glioblastoma multiforme (GBM) risk and outcome are correlated to polymorphisms in IL-4R gene loci." (PMID 34880868, 2021). "We focused on IL13RA2 as this gene encodes a monomeric IL4-independent and high grade glioma-associated IL13 receptor." (PMID 34447744, 2021). "The previously noted interaction between IL4 and sIL4RA continued to be associated with glioma in the presence of our univariate findings." (PMID 28594935, 2017). "Our findings suggest that IL4 and sIL4RA reduce glioma risk long before diagnosis and early gliomagenesis affects circulating immune function proteins." (PMID 26352148, 2015). "Previously researches have suggested the IL-4 polymorphisms were significantly associated with the risk of adult glioma." (PMID 23663500, 2013). "Given the tumour-trophic associations between these mediators and P2X7R in glioma, decreased expression of IL-4, IL-8, MMP-9 and PCNA maybe compensatory in nature." (PMID 41034696, 2025). "Our IL-4-related risk signature might also indicate a potential genetic pathway of NK cell exhaustion in the gliomas." (PMID 35203944, 2022). "The risk score could predict prognosis independently in glioma, which might provide a new insight for understanding the IL-4 involved mechanism of gliomas." (PMID 35203944, 2022). "Further identification of the molecular mechanisms that underlie the inhibition of TLR-induced responses in IL-4-exposed microglia may aid the design of strategies that aim to modulate innate immune responses in the brain, for example in gliomas." (PMID 34880868, 2021). "IL-4 plays a role in neuroinflammatory diseases like viral encephalitis and multiple sclerosis, but has also been implicated in the development and progression of gliomas." (PMID 34880868, 2021). "Moreover, to the best of our knowledge, the present study is the first time to investigate that IL-4 rs1801275 mutations affect the progression of glioma patients." (PMID 27495027, 2016). "Association between ranksa of IL4, sIL4RA, their interaction and glioblastoma and glioma." (PMID 26352148, 2015). "Similarly, IL-4 expression in glioma cells has been associated with reduced vascularisation and tumour growth, possibly influenced by tumour-associated fibroblasts (TAFs), which inhibit angiogenesis when stimulated by IL-4." (PMID 39325360, 2025).
glioma (continued). "Finally, although we conducted subgroup analyses for IL‐6, IL‐8, IL‐10, and TNF‐α with glioma risk to explore the potential sources of heterogeneity, high heterogeneity still existed in the studies of IL‐4, IL‐12, IL‐17, IL‐23, TGF‐β, and MCP‐1 based on the limited number of included studies." (PMID 31599129, 2019). "P2X7R was also upregulated in the glioma microenvironment and its expression was linked to the expression of VEGFB, MMP9, PCNA, IL-4 and IL-8." (PMID 41034696, 2025). "In vitro experiments have demonstrated that knockdown of TIM-1 expression inhibited the proliferation, migration, and invasion of glioma (U87, U251) cells and decreased the levels of TGF-β1, IL-6, IL-4, and IL-10 in gliomas." (PMID 38831760, 2024). "Interleukin-4 (IL4)-Pseudomonas exotoxin conjugate (IL4-PE) targets glioma cells by binding the IL4 receptor, which is highly expressed by malignant gliomas." (PMID 38261143, 2024). "MDNA55 is an engineered immunotoxin with permutated IL-4 conjugated to a modified pseudomonas exotoxin (PE), that targets glioma cells and immune suppressive cells highly expressing IL-4R." (PMID 37568717, 2023). "We firstly confirmed that 28 genes on the cellular response to IL-4 pathway had the ability to distinguish the key clinicopathological features of gliomas in both CGGA and TCGA datasets." (PMID 35203944, 2022). "REACTOME analyses further indicated IL4/IL3 pathways among associated genes, which can induce a shift towards immune-suppressive M2 phenotype of macrophages, linked to poor outcome in glioma." (PMID 35158950, 2022). "The DEGs were enriched in some Glioma-related processes, including “regulation of ion transport”, “interferon-gamma signaling”, and “interleukin-4 and interleukin-13 signaling”." (PMID 36138874, 2022). "Consensus clustering was firstly applied to identify that the cellular response to the IL-4 gene set had the ability to distinguish clinicopathological features of gliomas." (PMID 35203944, 2022). "Since then, a diverse set of biomarkers have been implicated as prognostic indicators in gliomas, including checkpoint molecules (PD-1, CTLA-4, TIM-3), growth/angiogenesis proteins (EGFR), and cytokines (TGF-β, IL-4, IL-13)." (PMID 35203944, 2022). "Meanwhile, the IL‐4 and IL‐10 released by microglia have anti‐inflammatory effects in the glioma environment." (PMID 33300633, 2021). "Okada and his group conducted clinical studies to test a vaccine constituted of IL-4-HSV-TK gene-modified autologous glioma cells, followed by systemic ganciclovir administration." (PMID 34439595, 2021). "Yu and colleagues experienced the antitumoral activity of IL4, which was administered to 12 nude mice affected by gliomas." (PMID 34439595, 2021). "It is believed that glioma-derived molecules, including IL-4, contribute to the shift of glioma-infiltrating microglia towards the tumor-supportive phenotype." (PMID 34082793, 2021). "The dual effects of GBM-targeting oncolytic viruses and immune-modulators have been much more effective than virus alone in preclinical tumor models, including in IL-12 secreting HSV and ADV armed with IL-4 for glioma, as well as in clinical trials." (PMID 33133514, 2020). "Nevertheless, IL-4 also modulates the brain microenvironment in glioma, with effects on tumor activated myeloid cells, and the promotion of tumor growth and invasiveness." (PMID 30813636, 2019). "In a mouse model of glioma elicited in nude mice by the injection of U87 human glioma cells, the co-transplantation of an IL-4-secreting cell line promoted a significantly increased survival and a massive infiltration by eosinophils." (PMID 30909395, 2019). "Since PD-L1 expression can be influenced by multiple factors, such as interferon (IFN)-γ and interleukin (IL)-4, more investigations regarding how this molecule is regulated in gliomas are required." (PMID 29643764, 2018). "Previous studies have reported that IL-4 blockade exhibits antitumor activity in rodent models of glioma." (PMID 29621254, 2018).
glioma (continued). "We observed that BDNF induced IL-15 production by microglia only upon treatment with IL-4 or co-culture with glioma cells." (PMID 29286001, 2017). "We demonstrate that BDNF stimulated the production of IL-15 in the brain of glioma-bearing mice, and specifically in microglia upon challenge with IL-4 or co-culture with glioma cells." (PMID 29286001, 2017). "With this aim, we studied microglia cultured in glioma-conditioned medium or treated with IL-4, as well as M/MΦ cells acutely isolated from glioma-bearing mice and from human glioma biopsies." (PMID 27054329, 2016). "Several studies have reported that SNPs in IL-4, IL-4R, and IL-13 were inversely correlated with the incidence of glioma." (PMID 27566584, 2016). "IL4R is found in abundance in glioma tumor cells and hence IL4 along with Pseudomonas exotoxin is used as immunotoxin therapy in clinical trials." (PMID 26390214, 2015). "In glioma cells, IL-4 signalling involves aberrant activation of STAT3 instead of STAT6 which are known to lead to enhanced cell proliferation, cell survival and angiogenesis in a number of human cancers." (PMID 26370624, 2015). "Glioma cells secrete factors such as IL-10, IL-4, IL-6, M-CSF, TGF-β, and prostaglandin E2 that suppress the immune functions of microglia when these cells are located inside the tumor." (PMID 26149494, 2015). "We do not, however, find any evidence for induction of IL13Rα2 through TNF/IL-4 or TNF/IL-13 cytokine regimens on glioma cell lines, either established (T98 or U251T) and/or low-passage primary lines (PBT003-4, PBT008, PBT017-4)." (PMID 24787244, 2014). "This resulted in a clinical trial using IL-4/HSV-TK gene-modified autologous glioma cells or fibroblasts." (PMID 26056588, 2014). "Two complementary clinical trials tested the use of IL-4 gene-transfected fibroblasts in combination with either autologous glioma cells alone or type 1 DCs loaded with autologous glioma lysate." (PMID 24804271, 2014). "Following these results, therapy of glioma by vaccination with autologous glioma cells engineered to produce IL-4 entered phase I clinical trials." (PMID 23493491, 2011). "In animal studies, therapeutic immunity to intracranial tumors has been induced by peripheral immunization with interleukin-4 (IL-4) transduced glioma cells." (PMID 20623001, 2010). "Granulocyte-macrophage colony stimulating factor (GM-CSF) and interleukin-4 (IL-4) transduced 9L gliomas also led to tumor immunization under similar conditions." (PMID 21437175, 2010). "The CTL population induced as a result of anti-CD25 immunotherapy expressed high levels of INF-γ and IL-4 in the group of glioma-bearing mice that had been treated, as compared to untreated animals." (PMID 20339520, 2009). "Taken together, these data demonstrate that significant P2X7R expression in high-grade glioma samples was positively associated with VEGFB expression, and inversely associated with IL-4, IL-8, MMP-9 and PCNA, demonstrating a potentially pro-tumour angiogenic capacity." (PMID 41034696, 2025). "Moreover, GBM microenvironment is enriched with GM-CSF, which acts on glioma-infiltrating myeloid cells and promotes immunosuppression through the upregulation of IL-4, an anti-inflammatory cytokine." (PMID 39594814, 2024). "In animal models, treated glioma cells resulted in more immunosuppressive than untreated samples as a consequence of the impressive overexpression of immunosuppressive cytokines including IL-4, IL-10, IL-6 and GM-CSF." (PMID 39594814, 2024). "Further, the combined IL-4 and TNF-α treatment had been found to cause synergistic augmentation in PD-L1-expression in renal carcinoma cells while the inductive effect of IL-1β on PD-L1-expression had been demonstrated in lung cancer and glioma cell lines." (PMID 39445017, 2024).